TET1 (tet methylcytosine dioxygenase 1)
Diseases named in the same sentence as TET1 in open-access papers (continued):
Sharing a sentence is not in itself a finding about the gene and the disease.
ovarian carcinoma (20 papers, 2017 to 2025). A malignant neoplasm originating from the surface ovarian epithelium. "In fact, high levels of TET1 were associated with worse overall survival in uterine and ovarian cancers as well." (PMID 34209564, 2021). "Conversely, higher TET1 expression in ovarian cancer is associated with poorer survival." (PMID 38929174, 2024). "Experimental restoration of TET1 repression in ovarian cancer cells could also inhibit the growth of ovarian cancer cells by reversing DNA-methylation-associated silencing of SFPR2 and DKK1—two endogenous inhibitors of WNT signaling." (PMID 31426393, 2019). "For example, TET1 acts as a tumor suppressor in colon and pancreatic cancers, but as an oncogenic factor in ovarian cancer, AML, and medulloblastoma." (PMID 40599235, 2025). "The present study aimed to analyze the metabolism of TET1-reprogrammed ovarian CSCs and explore the possibility of a metabolic intervention for ovarian cancer treatment." (PMID 38929174, 2024). "Gene expression profiles after TET1 expression in the different histotypes of ovarian cancer were further determined using qPCR." (PMID 38929174, 2024). "Our findings supported the potential use of complex I inhibitors in future ovarian cancer treatment, especially in the TET1-high expression subgroup." (PMID 38929174, 2024). "In our previous study, we demonstrated that TET1 reprogrammed the ovarian cancer epigenome, increased stem properties, and activated various regulatory networks, including metabolic networks." (PMID 38929174, 2024). "TET1 expression was shown to correlate with cell migration, cancer stemness tumorigenicity, and poor survivals in epithelial ovarian cancer and in TNBCs." (PMID 34209564, 2021). "In epithelial ovarian cancer, research has revealed that ten-eleven translocation 1 (TET1) inhibits cell migration and invasion by upregulating DKK1 28, which is partly consistent with our study." (PMID 33613114, 2021). "In ovarian cancer, overexpression of TET1 increases chemoresistance partially through promoting epithelial-to-mesenchymal transition mediated by the induction of vimentin level." (PMID 32528872, 2020). "Han X showed that TET1 promotes cisplatin-resistance via demethylating the vimentin promoter in ovarian cancer." (PMID 31656201, 2019). "In some cases, TET1 upregulation was also reported in aggressive ovarian cancer; however, the basis of such overexpression and it’s implication in patient survival through specific pathways remains undefined." (PMID 31426393, 2019). "In general, TET1 expression is reduced in invasive ovarian cancer as compared to less invasive stages." (PMID 31426393, 2019). "The levels of 5hmC were shown to be significantly increased in TET1-overexpressing ovarian cancer cells, which was consistent with the results obtained using transient TET1 or TET3 overexpression." (PMID 29156803, 2017). "TET1 is responsible for 5mC to 5hmC conversion, and we attempted to elucidate the effects of TET1 overexpression on 5hmC levels in ovarian cancer cells." (PMID 29156803, 2017). "Here, we show that ectopic expression of TET1 increased 5hmC levels, and inhibited proliferation and colony formation in ovarian cancer cell lines." (PMID 29156803, 2017). "The obtained results demonstrated that the inhibition of TET1 expression in ovarian cancer cells induces tumor proliferation in vivo." (PMID 29156803, 2017). "We next analyzed the effect of TET1 overexpression on ovarian cancer cell proliferation and showed that this leads to a remarkable reduction in cell growth, compared with that in the control samples." (PMID 29156803, 2017). "Further delineation of the mechanistic link between TET1, RASSF5, and 5hmC production should allow a better understanding of TET1 functions in ovarian cancer cells." (PMID 29156803, 2017). "In this study, we demonstrated that TET1 expression is downregulated in most ovarian cancer tissues and cells." (PMID 29156803, 2017).
ovarian carcinoma (continued). "At the protein level, as compared with other cells, TET1 was highly expressed in A2780 cells, but it was weakly expressed in ES-2 cell, which was consistent with the observed 5hmC levels in ovarian cancer cells." (PMID 29156803, 2017). "To elucidate the effects of TET1 on the ovarian cancer cell apoptosis, we measured pH2AX and cleaved caspase 3 levels by IHC and immunofluorescence staining." (PMID 29156803, 2017). "Our findings demonstrated that, epigenetically, TET1 reprogrammed ovarian cancer and altered the mitochondrial OXPHOS pathway to activate respiration rather than glycolysis for energy production, suggesting metabolic plasticity via epigenetic regulation in ovarian CSCs." (PMID 38929174, 2024). "Our previous investigations revealed that TET1 reprogrammed the epigenomics of ovarian cancer cells, leading to a stem-like state that activated various regulatory networks, including the developmental, immune response, hormone response, and metabolic networks." (PMID 38929174, 2024). "Ten-eleven translocation 1 (TET1), an important DNA demethylase, was found to be overexpressed in cisplatin-resistant ovarian cancer cells and could induce partial EMT by increasing vimentin expression through demethylation of the vimentin promoter." (PMID 36313710, 2022). "In contrast, RASSF5 upregulation by ten-eleven translocation 1 (TET1)-mediated demethylation may result in the suppression of ovarian cancer cell proliferation." (PMID 34681900, 2021). "TET1 suppressed pancreatic tumor proliferation, migration, and invasion in vivo and in vitro via inhibiting the Wnt/β-catenin signaling pathway, which is consistent with results found for colon and ovarian cancer." (PMID 31399111, 2019). "Furthermore, we showed that TET1 overexpression leads to an increase in 5hmC levels and inhibits cell proliferation and colony formation in several ovarian cancer cell lines, while TET1 silencing induced the opposite effects in vitro and in vivo." (PMID 29156803, 2017). "Therefore, we selected ES-2 cell line, derived from a CCC, for TET1-overexpression experiments, and demonstrated that this leads to an increase in 5hmC levels and the inhibition of ovarian cancer growth in vivo and in vitro." (PMID 29156803, 2017). "Our results for TET1 expression in ovarian cancer cell have clinical and therapeutic implications." (PMID 29156803, 2017). "Furthermore, in vitro and in vivo functional studies demonstrated that TET1 overexpression is necessary for the suppression of ovarian cancer growth, whereas depletion of TET1 expression had the opposite effect." (PMID 29156803, 2017). "However, the role of TET1 in ovarian cancer remains controversial." (PMID 40599235, 2025). "Therefore, we hypothesized that simultaneous targeting by the mitochondrial complex I inhibitor and the TET1-mediated immune modulator CK2α may have additive or synergistic effects on ovarian cancer cell growth inhibition." (PMID 38929174, 2024). "However, the understanding of TET1 in ovarian cancer remains limited and controversial." (PMID 38929174, 2024). "Interestingly, a global reduction in the level of 5hmC could be revered using epigenetic approaches involving DNMT inhibitors and thus, supports the notion of TET1’s involvement in reprogramming ovarian cancer epigenome." (PMID 31426393, 2019). "Here, we demonstrated that TET1 effect the methylation of DNA in human ovarian cancer tissues and cells, and that the expression of TET1 and 5hmC levels were significantly decreased in ovarian cancer tissue and cells, in comparison with those in the normal, healthy tissue." (PMID 29156803, 2017). "However, there is opposing evidence as to the role of TET1 in EMT‐induced chemoresistance: TET1 has been reported to promote cisplatin resistance through its induction of EMT in ovarian cancer, but act as a barrier against EMT in mammary epithelial cells by derepressing the miR‐200 promoter." (PMID 28544151, 2017).
ovarian carcinoma (continued). "Thus, small molecules that can increase TET1 activity may have the therapeutic potential to enhance the effect of chemotherapy for ovarian cancer patients." (PMID 29156803, 2017). "Additionally, to examine whether TET1 overexpression inhibits ovarian cancer growth by increasing RASSF5 levels, the effects of TET1 expression on RASSF5 levels were determined." (PMID 29156803, 2017). "Further analyses confirmed that RASSF5 expression increases in TET1-overexpressing ovarian cancer cells, but the obtained results suggested that other TET1 downstream targets may also mediate the effects of this molecule on ovarian cancer cell proliferation and colony forming ability." (PMID 29156803, 2017). "In contrast to decreased expression of TET1/2 in cancers, it was found that TET3 expression was upregulated in ovarian cancer, and its high expression was correlated with poor clinicopathological features." (PMID 34948036, 2021). "In our study, DKKs and SFRPs were all upregulated in response to TET1 overexpression except DKK1, which is a similar result obtain by two other studies in colon and ovarian cancer." (PMID 31399111, 2019). "Additionally, this indicates that TET1 activity and 5hmC levels play important roles in ovarian cancer development and progression, and that 5hmC levels may represent a valuable biomarker for the diagnosis of ovarian cancer." (PMID 29156803, 2017). "TET1 overexpression was shown to increase RASSF5 promoter demethylation, which further stimulates RASSF5 expression, leading to the suppression of ovarian cancer cell proliferation and colony formation." (PMID 29156803, 2017). "However, TET1 roles in ovarian cancer cell growth are unknown." (PMID 29156803, 2017). "Altogether, TET1-reprogrammed ovarian cancer stem cells shifted the energy source to OXPHOS, which suggested that metabolic intervention might be a novel strategy for ovarian cancer treatment." (PMID 38929174, 2024). "To understand how TET1 expression inhibits ovarian cancer growth, we performed a genome-wide RNA-seq analysis of total mRNA isolated from ES-2 cells treated with paclitaxel (0.01 μg/mL) (EVTAXOL) or without it (EV) for 24 h and from TET1-overexpressing ES-2 (ET) or empty vector-carrying (EV) cells." (PMID 29156803, 2017).
Obesity (18 papers, 2011 to 2025). Accumulation of substantial excess body fat. "The TET1-centric pathway in our working model is also linked with inflammation, another major hallmark of obesity." (PMID 37231419, 2023). "This pathway is active in diet-induced obese mouse models of TNBC, showing that obesity-associated inflammatory signals activate the TET1-NANOG system in vivo." (PMID 37231419, 2023). "Adipose-specific TET1 loss-of-function led to increased energy expenditure and protection from diet-induced obesity, insulin resistance, and glucose tolerance." (PMID 32855402, 2020). "In our prior study, we show that reactive oxygen species (ROS) generation via CoCl2 or IL-6 treatment enhances this TET1 pathway and ROS neutralization via catalase represses this pathway, potentially explaining the inflammatory hallmark of clinical obesity as a risk factor for TNBC." (PMID 37231419, 2023). "Next, we asked whether adipose-selective Tet1 deficiency confers protection against diet-induced obesity and impaired glucose tolerance by placing cohort mice on a high-fat diet (HFD, 60% calories from fat)." (PMID 32855402, 2020). "Furthermore, in 2007, the FTO (fat mass and obesity associated) gene was found to encode a functional homologue of AlkB, and two more genes, TET1 and TET2, suggested possibility as a similar mechanism." (PMID 21285982, 2011). "We observe a difference in the mRNA expression of Tet1 and Tet3 in the cerebellum in males exposed to maternal obesity compared with controls." (PMID 40373797, 2025). "For the impacts of TET1 on MASLD progression, it has been suggested that depleting adipocyte TET1 protects mice from MASLD through suppressing obesity and insulin resistance." (PMID 40164757, 2025). "Phenotypically, adipocyte-specific Tet1 knockout increased energy expenditure and protected against diet-induced obesity and insulin resistance." (PMID 38216792, 2024). "In our previous reports, we observe that diet-induced obesity (DIO) can upregulate pathway members TET1 and MBD2_v2 levels." (PMID 37231419, 2023). "Vitamin-C modulates TET-dependent 5hmC formation in embryonic stem cells and fibroblasts, changing gene expression at loci that alter cell fate, and it reverses the obesity-prone phenotype of TET1-insufficient HFD mice." (PMID 37231414, 2023). "Together, these data demonstrate that obesity and diabetes negatively modulate the glomerular expression of TET1 and TET3 only in females." (PMID 37091852, 2023). "In first step, obesity triggers systemic hyperglycemia, which activates TET1 to produce higher levels of the DNA binding protein TARDBP via increased OGT substrate levels." (PMID 37231419, 2023). "Oral intake of vitamin C normalizes DNA methylation levels, promotes lipolysis, and decreases obesity in HFD-fed Tet1+/− mice." (PMID 35956309, 2022). "The role of TET1 has been recently explored in cancer and developmental diseases; however, there is an apparent lack in studying this mechanism in the context of obesity and vascular dysfunction." (PMID 34440238, 2021). "Adipose-selective Tet1 knockout mice generated by using Fabp4-Cre improves cold tolerance and increases energy expenditure and protects against diet-induced obesity and insulin resistance." (PMID 32855402, 2020). "Efforts are underway to study the role of TET1 in cancer and developmental diseases, however there is an obvious lack in studies investigating this mechanism in the context of obesity." (PMID 31935962, 2020). "The role of TET1 in obesity was further illustrated in 2022." (PMID 40520993, 2025). "TET1 has also been identified as a significant epigenetic regulator specifically targeting beige adipocytes to suppress the thermogenic gene program, offering potential therapeutic avenues for enhancing energy expenditure in metabolic disorders like obesity." (PMID 40520993, 2025). "We have found that TET1 KO suppressed diet induced obesity and MASLD." (PMID 40164757, 2025).
Obesity (continued). "Knockout (KO) of TET1 slightly improved diet induced obesity and glucose homeostasis." (PMID 40164757, 2025). "In mouse adipocytes, it was shown that TET1 coordinates with histone deacetylase 1 (HDAC1) to epigenetically suppress thermogenic gene transcription and that adipocyte-specific Tet1 knockout in mice increases energy expenditure and protects against diet-induced obesity and insulin resistance." (PMID 38216792, 2024). "Our new data suggests, potentially for the first time, that two distinct physiological hallmarks of obesity—systemic hyperglycemia and chronic inflammation—might converge on this TET1-driven pathway to drive cancer stem-like cell induction." (PMID 37231419, 2023). "We speculated that the hypermethylation of Pparα resulted from the decreased Tet1/2 expression in mothers given a HFD during gestation, thereby causing lipid metabolism disorders and obesity." (PMID 33955677, 2021). "In the current study, we explored the role of TET1 enzyme in hypoxia-induced hypomethylation using primary adipocytes, hoping to reveal the mechanism by which dysfunctional adipose tissues produce excess inflammatory cytokines in obesity and comorbidities." (PMID 31935962, 2020). "The DNA demethylase ten-eleven translocation 1 (TET1) overexpression impairs the thermogenic capacity of beige adipocytes and contributes to obesity development." (PMID 40729009, 2025). "Moreover, we observed higher expression levels in SAT compared to OVAT for the erasers TET1, TET2, and TET3, while the expression is lower across tissue depots among subjects with obesity." (PMID 41030849, 2025).
prostate carcinoma (17 papers, 2016 to 2025). A carcinoma that arises from epithelial cells of the prostate gland. "The clinical significance of these findings was validated in a separate prostate cancer cohort, where reduced TET1 mRNA levels were associated with poorer metastasis-free survival." (PMID 40520993, 2025). "The study also identified a substantial decrease in hydroxymethylated DNA within tumor tissues, highlighting TET1's crucial role in DNA modification and its potential impact on prostate cancer progression." (PMID 40520993, 2025). "TET1 activation in prostate cancer also triggers the expression of genes involved in chromatin remodeling, mitosis, anti-viral processes, and stem cell pluripotency, with many of these genes showing associated promoter hypomethylation." (PMID 40520993, 2025). "They found that TET1 protein levels were consistently lower in tumor tissues compared with non-tumor tissues, indicating TET1's significant role in preventing prostate cancer invasion." (PMID 40520993, 2025). "As another example, the circRNA UCK2 simultaneously inhibits invasion and enzalutamide resistance by upregulating TET1 in prostate cancer." (PMID 32799866, 2020). "In prostate cancer, compared to patients with high TET1 mRNA levels, patients with low TET1 mRNA levels possess a doubled risk at developing metastases; TET1 catalytic activity plays a suppressive role in prostate cancer." (PMID 27557497, 2016). "Studies have shown a reduction in TET1/2 and 5hmC levels in prostate cancer." (PMID 40599235, 2025). "TET1 suppresses prostate cancer invasion by activating TIMPs." (PMID 40520993, 2025). "Interestingly, FOXA1 was shown to induce TET1 expression through direct binding to its cis-regulatory elements, which in turn led to binding of TET1 to FOXA1 sites mediating local DNA demethylation in prostate cancer cells." (PMID 35331302, 2022). "TET1 inhibits prostate cancer invasion by activating tissue inhibitors of metalloproteinases." (PMID 34656178, 2021). "Furthermore, researchers have examined how DNMTs and TETs may contribute to disease progression and established roles for increased DNMTs in mouse models of prostate cancer and that TET1 for example is disrupted by copy number changes correlating with reduced 5hMC levels in prostate cancer samples." (PMID 28216563, 2017). "The biological significance of miR‐200c and miR‐141 expression in prostate cancer cells was assessed by a series of in vitro bioassays and the effect on proposed targets DNMT3A and TET1/TET3 was investigated." (PMID 27198154, 2016). "The dysregulation of HERV activation restriction genes has also been found in other cancers, such as the overexpression of TET1, TET3, and APOBEC3B but downregulation of APOBEC3C, 3G, 3D, 3H, and C2 in prostate cancer, and different cancers may involve different activation restriction genes." (PMID 37509325, 2023).